IFNG (interferon gamma)
Diseases named in the same sentence as IFNG in open-access papers (continued):
Sharing a sentence is not in itself a finding about the gene and the disease.
tumor (continued). "Inhibition of IFNγ around leaky blood vessels is an effective way to promote vascular integrity and drug penetration in tumour." (PMID 37056922, 2023). "We first employed our multi-scale models to study a long-range IFNγ spreading scenario within a T cell-infiltrated tumor embedded in a uniform TGFβ field." (PMID 37638024, 2023). "By KEGG analysis in tumor signal pathways, we found that B cell maker genes were mainly enriched in estrogen response, interferon-gamma response, androgen response, TNF-α signaling via NK-κB, and complement response." (PMID 37889543, 2023). "NK cells are considered a part of the innate immune system and exercise their function through the secretion of perforins, granzymes, TNF-α, and interferon gamma (IFN-γ) leading to tumor cell lysis." (PMID 37174089, 2023). "CCX559 significantly and robustly enhanced primary human T cell responses in vitro, measured by IFNγ secretion and tumor cell killing." (PMID 37285333, 2023). "The compound also induced T cell co-stimulatory molecules (CD28; CD40L; OX40; CD38), generating overall a marked anti-tumor activity with enhanced IFNγ, IL-2 and TNF expression." (PMID 37296860, 2023). "The number of IFNγ+ T cells was inversely correlated with tumor volume, consistent with their presence promoting tumor clearance." (PMID 37543621, 2023). "Their findings suggest interferon-gamma (IFN-γ)-based activation of tumor- infiltrating lymphocytes (TILs) following neoadjuvant ICI treatment." (PMID 37092448, 2023). "BA, BE, and its derivatives seem to cover all the potential complications of IL-6/IFNγ interplay in the tumor microenvironment." (PMID 36282372, 2023). "It was showed that combination of anti-PD-1 and YIV-906 administration significantly reduced IDO and M-MDSC of Hepa 1–6 tumor, enhanced IFNg action, polarized macrophages toward M1 type, and enhanced anti-tumor effects." (PMID 37217620, 2023). "MDSC depletion induced by 5FU led to increased interferon γ(IFNγ) secretion by tumor-specific CD8+ cells, stimulating a T cell-dependent adaptive immune response." (PMID 36039609, 2023). "Analyses of serum cytokine relationships with clinical response showed a significant correlation between peak serum IFNγ levels and tumor reduction." (PMID 36624315, 2023). "Among the effector functions of CD8+ T cells, it is important to mention the release of IL-2 (recruiting NK cells) and interferon-gamma (disrupting tumor proliferation and angiogenesis)." (PMID 36768649, 2023). "We found that tumor-localized [89Zr]Zr-DFO-anti-IFNγ tracer uptake correlated with ICI treatment outcomes in CT26 tumor-bearing mice." (PMID 38130991, 2023). "IFNγ is a proinflammatory cytokine that can directly induce apoptosis in tumor cells and stimulate innate and adaptive immune activation." (PMID 37958404, 2023). "Our results demonstrate that DMKG and radiotherapy significantly enhance the infiltration of IFNγ + CD8 + T cells into the tumor area and augment PD-L1 expression in the tumor vicinity." (PMID 37438720, 2023). "Cytokine expression was critical in the MOA of ITI-3000 as CD4 T cell-mediated IFNγ production was essential for the anti-tumor immune response induced by vaccination." (PMID 37711623, 2023). "We found that C3 had stronger tumor-killing activity, as evidenced by either the IFN-γ pathway and the expression of the IFNG gene or the cytotoxicity score." (PMID 36739412, 2023). "Our results provide a basis for tissue-specific delivery of IFNγ blockade for the improvement of tumor chemotherapy." (PMID 37056922, 2023). "The mechanisms include failure of antigen presentation, failure of immune cells to infiltrate the tumor, failure of the interferon-gamma pathway in the tumor, and the contribution of immune suppressive cells." (PMID 36793737, 2023).
tumor (continued). "Based on our own findings as well as emerging data in the CAR T-cell field, we reasoned that our clinical lead TAG72-CAR T cell’s superior performance against solid tumors is due to its ability to secrete high levels of IFNγ and enhance tumor cell killing." (PMID 37550294, 2023). "These interleukins trigger the cytotoxic activities of NK and cytotoxic T lymphocytes (releasing granzymes and perforins to kill tumour cells) and induce the release of IFNγ (inducing apoptosis of tumour cells)." (PMID 36765809, 2023). "We show that NKG2D ligand expression shapes the inflammatory landscape and disease prognosis of CRC by enhancing IFNγ secretion in the tumor microenvironment (TME)." (PMID 36980678, 2023). "Further, baseline ctDNA combined with other biomarkers (tumor molecular burden, IFNγ) were more predictive of recurrence than any other biomarker alone." (PMID 37328818, 2023). "Cpt-DNA adducts within tumour tissues were increased by anti-IFNγ treatment and the effective rate of drug delivery was increased by about 113% (cisplatin: 2.55%; cisplatin combined with anti-IFNγ: 5.44%), as shown by immunostaining." (PMID 37056922, 2023). "Unfortunately, ICI treatment on days 5 and 8 yielded inadequate residual tumor tissue within the treated cohort to extract quality RNA for downstream analysis of IFNγ expression and downstream signaling." (PMID 38130991, 2023). "FAK-/- tumours exhibited a significant increase in the number of cells positive for IFNγ expression when compared with FAK-wt tumours (left), with almost all of the IFNγ being secreted by immune (CD45+) cells (right)." (PMID 36977556, 2023). "For instance, interferon gamma (IFN)-mediated ferroptosis of tumor cells is one way that CD8+ T lymphocytes contribute to the suppression of malignancies." (PMID 37480146, 2023). "The proportion of effector T lymphocyte interferon‐gamma IFN‐γ+CD8+ T cells inside the tumor was assessed." (PMID 37660174, 2023). "Interferon-gamma (IFN-γ) is generally considered as a pro-inflammatory cytokine which mediates anti-tumor immune response." (PMID 38007483, 2023). "Previous studies have indicated that blockade of CD137L reverse signaling promotes intra-tumoral differentiation of IFNγ-producing cytotoxic T cells, IL12-producing CD103+ DC, and type 1 tumor-associated macrophages to suppress tumor growth." (PMID 37334375, 2023). "Unexpectedly, we observed increased proportions of monocytes and IFNγ+CD44+ CD4+ T cells in anti–PD-1-treated KB1P tumor-bearing mice." (PMID 36480166, 2023). "IFNγ, which is predominantly secreted by T cells, is a key regulator in the tumor immune response and exerts complex effects on the tumor microenvironment." (PMID 36894639, 2023). "IFNγ can escape the immune synapse and induce signaling in tumor cells several layers away from the site of secretion." (PMID 37803324, 2023). "In KitV558Δ/+ mouse GIST model, the combination of imatinib and CTLA-4 inhibitors enhanced the infiltration of CD8+ T cells evidently, strengthened the production of IFNγ markedly, and reduced the tumor size significantly." (PMID 37072770, 2023). "The study further revealed that the antitumor mechanism of OMVs is reliant on interferon-gamma (IFN-γ) production in the tumor microenvironment and CXCL10 expression to attract effector T cells." (PMID 37111538, 2023). "The data showed that NKG2D-CAR-NK92 cells with GPR116 receptor knockdown released more cytotoxic substances such as GzmB and IFNγ, and suppressed tumor growth more effectively both in vitro and in vivo compared to NKG2D-CAR-NK92 cells." (PMID 36895027, 2023). "The tumor modulation role of IFNγ has been widely elucidated in diverse types of both hematological and solid malignancies including PC18." (PMID 37816781, 2023). "Interferon-gamma (IFN-γ) released by activated T-cells can upregulate the tumor cell surface protein PD-L1." (PMID 38106415, 2023).
tumor (continued). "Tumor infiltrated CD8+ T cells, the main player of anti-tumor immunity and producers of interferon gamma (IFN-γ), is highly relevant for predicting the therapeutic response to anti-PD-1/PD-L1 therapy." (PMID 37853469, 2023). "In this study, we found that cisplatin-induced tumour vascular damage was largely dependent on IFNγ." (PMID 37056922, 2023). "Based on the observation of ~10 pg/g IFNγ in the tumour tissues, and our own experiences in usage of anti-IFNγ antibodies (clone: R46A2) 17, 36, we applied anti-IFNγ antibody at 2.5 mg/kg." (PMID 37056922, 2023). "We used intravital two-photon microscopy in an IFNγ-YFP reporter mouse inoculated with EMT6 tumor cells." (PMID 37543621, 2023). "A comparative analysis revealed a notable shift in the ratio of IFNγ+ CD8+ to IL-17A+ CD8+ T cell frequencies (Tumor- 31.2% versus 1.4%; STM- 17.3% versus 0.4%)." (PMID 38074634, 2023). "Consistent with Stem-like T cells being an important target of IFNγ for inhibiting long-term anti-tumor responses, WT stem-like T cells displayed higher IFNγR expression compared to all other intra-tumoral CD8 T cell subsets." (PMID 36658158, 2023). "Cytokine IFNγ produced by T-cells, is considered as a molecule with dual roles, which promotes anti-tumor immunity and immune evasion." (PMID 38016985, 2023). "Through secretion of IFNγ, they enhance presentation of pHLA complexes on tumor cells and directly support CD8 T cells." (PMID 37810959, 2023). "CAR-T cells with a high level of IFNγ showed poor anti-tumor activity due to upregulation of PD-L1 in GBM cells." (PMID 37443804, 2023). "The serum cytokine response profile indicated an IFNγ-driven mechanism of action as well as emerging biomarkers of anti-tumor response." (PMID 36624315, 2023). "Many cancers upregulate PD-L1, which is even enhanced by IFNγ secretion by T cells upon tumor cell engagement." (PMID 37810959, 2023). "Th1 cells have been well-recognized to mediate anti-tumor effects, as they produce effector cytokines IL-2 and IFNγ." (PMID 37771596, 2023). "Their ability to produce type 1 cytokines (IFNγ, TNFα) as well as cytotoxic effector molecules endows them with potential anti-tumor functions." (PMID 37020559, 2023). "Of note, it has been previously demonstrated that tumour-infiltrating cytotoxic T lymphocytes can secrete IFNγ and enhance PD-1 expression, leading to the upregulation of PD-L1 in tumour cells." (PMID 37370741, 2023). "In the process of cyclopamine-induced tumour rejection, macrophages are activated to produce IFNγ and inhibit angiogenesis." (PMID 37056922, 2023). "To evaluate the cellular immune responses in rats cured of the tumor, we measured the splenic T cell proliferation rate and the number of splenocytes producing IFNγ in response to in vitro restimulation with recombinant rat BORIS." (PMID 36983050, 2023). "As anticipated, our model predicts the entire tumor to be exposed to IFNγ due to the substantial IFNγ spreading." (PMID 37638024, 2023). "Further in vitro experiments revealed that IFNγ + IL1β/TNFα increased the elongation and migration of treated tumor cells." (PMID 37169743, 2023). "Considering that IFNγ is a key mediator of anti-tumour immunity, we applied an anti-IFNγ antibody at different time points to screen the time window for beneficial outcomes." (PMID 37056922, 2023). "This agrees with single‐cell transcriptome analyses that have detected expression of genes up‐regulated by IL4 and IFNγ in some tumor‐derived macrophages." (PMID 37199012, 2023). "They kill tumor cells in an antigen-specific MHC class II-restricted manner not only by cytolysis but also by release of IFNγ." (PMID 37965314, 2023). "Consistent with the preceding findings, IFNγ secretion was increased both in the primary and the rechallenged tumor rejective responses, and serum TNFα level was increased significantly during tumor rechallenge." (PMID 37407600, 2023).
tumor (continued). "IFNg-induced downregulation of CXCR4 was previously shown to result in reduced tumor metastasis and virus replication." (PMID 38086798, 2023). "CREKA-lipo-anti-IFNγ combined with cisplatin reduced tumour volume compared with those reduced by cisplatin alone, while lactate abrogated the effect of CREKA-lipo-anti-IFNγ." (PMID 37056922, 2023). "OT-I cells with effector-like phenotypes showed greater accumulation in glutamine-treated tumours, and also showed increased T-bet expression and higher frequencies of granzyme B- or IFNγ- and TNF-co-expressing cells." (PMID 37407815, 2023). "It promoted the recruitment of MDSCs, resulting in a more immunosuppressive TME to abolish the activity of anti-tumor IFNγ+T-cell immunity." (PMID 38313431, 2023). "Various other mechanisms of IFNγ-mediated anti-tumour immunity have been proposed, for example by decreasing cancer stem cells in the 4T1 mouse model of breast cancer." (PMID 37455828, 2023). "In the single-cell sequencing data, the distribution of expression of IFNG in the tumor was analyzed, and IFNG was mainly expressed by T cells in tumor tissues." (PMID 37154982, 2023). "Recently, elevated NOS2 and COX2 expression was discovered in distinct immune and tumor cells upon treatment with IFNγ and cytokines or TLR4 agonists, consistent with feedforward NOS2/COX2 signaling as previously reported." (PMID 37169743, 2023). "Normally, the adaptive and innate immune systems can detect tumor cells and destroy them through NK cells, secretion of interferon gamma (IFN-γ), and activating DCs." (PMID 36937115, 2023). "For exhaustion related to the CD274/PDCD1 axis, this is clearly justified because IFNG can induce upregulation of CD274 on tumor cells." (PMID 37182110, 2023). "In another study, the expression of IFNγ-induced chemokine CXCL10 in the tumor negatively correlated with tumor size and microvessel density (MVD) but positively correlated with the number of infiltrating CD8+ cells." (PMID 37445941, 2023). "Quantification of the IFNγ MCP program in all animals revealed a significant enrichment of IFNγ MCP program activity following combination treatment in tumor cells, myeloid cells, and CAFs." (PMID 37543621, 2023). "Upon binding to its receptor (expressed on CD4+, CD8+T-cells and NK-cells), IFNγ can trigger biologically relevant anti-tumor activities." (PMID 36839699, 2023). "Loss-of-function mutations in the IFNγ-sensing pathway were significantly enriched among the most insensitive tumours, which confirmed that IFNγ sensing is required for AC484-mediated tumour growth inhibition." (PMID 37794185, 2023). "IFNγ-induced internalisation of VE-cadherin is a major mechanism of cisplatin-induced vascular leakage in tumours." (PMID 37056922, 2023). "Once activated, these cells predominantly produce tumour-rejecting cytokines such as IFNγ, release cytotoxic granules and kill target tumour cells." (PMID 37311978, 2023). "Cytokine analysis of tumor extracts additionally showed that vaccination with ITI-3000 induced significant expression of IFNγ, IL-1β, IL-2, and TNFα, indicative of a strong anti-tumor immune response." (PMID 37711623, 2023). "Cisplatin treatment was found to promote an increase in the expression of IFNγ, enhance endothelial cell glycolysis and lactic acid production, promote VE-cadherin endocytosis, and promote the disruption of tumour vascular integrity." (PMID 37056922, 2023). "Cytotoxic lymphocytes, such as CD8+ and CD4+ cells, alongside their respective cytokine interferon-gamma (IFN-γ), play a significant role as tumor antagonist effectors." (PMID 38328405, 2023). "In contrast, lactic acid in the tumor microenvironment lowered PPARγ levels in iNKT cells, abrogating IFNγ production." (PMID 37686465, 2023). "To interrogate the impact of IFNγ on the anti-tumor response induced by combination treatment, we performed an IFNγ blocking experiment." (PMID 37543621, 2023).
tumor (continued). "IL-4, TGFβ and IL-8 were assessed in low amounts (471 to 820 pg/mg of tumor); CCL2, IL-12, IL-6 and IL-10 in moderate amounts (2825 to 3440 pg/mg of tumor); and IFNγ, TNFα, IL-1β and IL-2 in high amounts (6293 to 13,492 pg/mg of tumor)." (PMID 37526660, 2023). "CD4+ Th1 cells and CD8+ T-cells are generally regarded as tumor-suppressant, majorly through the activity of interferon gamma (IFN-γ)." (PMID 37681925, 2023). "IL-12 can also induce IFNγ-independent CRC tumour rejection via activation of CD8+ T cells, a process that is dependent on CD4+ T cells and granulocyte-macrophage colony-stimulating factor (GM-CSF)." (PMID 37455828, 2023). "IFNγ is secreted primarily by innate NK and NKT cells, and adaptive Th1-skewed CD4 and cytotoxic CD8 T cells, and IFNγ is a necessary component of an efficacious anti-tumor immune response." (PMID 38130991, 2023). "Taken together, this demonstrates that the TRDV1-containing TR 29.ct2 confers binding of the T cells to the tumor cells and induces a very strong IFNγ response." (PMID 38077312, 2023). "Described by Gordon-Alonso and colleagues, secreted Gal-3 accumulates in the tumour extracellular matrix and blocks diffusion of IFNγ by binding its glycans." (PMID 36817445, 2023). "As for IDO, PD1 and PD-L1 are induced by IFNγ, and the interplay between these two systems contributes to their immunosuppressant and tumor-inhibitory activity." (PMID 37296860, 2023). "For example, the expression of SERPINB9, a potential drug target and a member of the T-cell dysfunction signature genes, is upregulated in tumor cells by interferon gamma (IFNγ, encoded by the IFNG gene) in the tumor microenvironment." (PMID 37106127, 2023). "TBBPA has also proven to alter the tumor destroying function of NK lymphocytes, the secretion of IL-1β, and the inflammatory cytokines interferon gamma (IFNγ)." (PMID 36985477, 2023). "The presence of PDL1 on the surface of tumor cells can be heightened by interferon-gamma (IFN-γ) produced by activated T cells." (PMID 38003938, 2023). "IFNγ is a cytokine secreted by tumour–infiltrating T cells and induces PD‐L1 expression by stimulating the JAK/STAT signalling pathway." (PMID 36519208, 2023). "The idea behind this project is to use irradiated seYTS cells for the killing and IFNγ secretion following incubation with CD48-positive tumor cells." (PMID 37609636, 2023). "Some have even noted the “paradoxical” role of IFNG in tumor progression, paradoxical in the sense that IFNG can have both pro-tumor and anti-tumor effects." (PMID 37182110, 2023). "Lastly both rIL‐1α and IL‐1α‐MPs significantly increased IFNγ, which is a prominent cytokine in anti‐tumor immunity compared to control and Blank MP‐treated mice." (PMID 37206237, 2023). "Altogether, these data demonstrate that—unless immunosurveillance results in tumor eradication—IFNγ signaling can promote the accumulation of aggressive CSCs underlying rapid tumor progression." (PMID 37604810, 2023). "The upregulation of PD-L1 due to IFNγ is addressed by PD-L1 inhibitors; therefore, the anti-tumor effects of IFNγ can be achieved while avoiding the pro-tumor effects." (PMID 38201559, 2023). "Vaccinated mice that had a complete tumor regression after the first C3.43 challenge and remained tumor-free after the second C3.43 challenge generated numerous IFNγ-positive T cells in response to stimulation with both E6 and E7 peptide libraries." (PMID 37503351, 2023). "Whilst CD8+ T cells, like Th1 cells, are potent producers of IFNγ, they additionally exert direct cytotoxicity on tumour cells through Fas ligand (FasL) or perforin and granzyme which can be further enhanced in response to IFNγ signalling." (PMID 37455828, 2023). "We also observed dose-dependent enhancement of tumor cell killing with increasing concentrations of recombinant huIL12, which resulted in increased production of IFNγ by CAR T cells as determined by ELISA at the assay endpoint (right, and 2c)." (PMID 37550294, 2023).